RN7SL209P (RNA, 7SL, cytoplasmic 209, pseudogene)
Gene: Miscellaneous RNA gene on chromosome 15 (101,773,238 to 101,773,513, reverse strand). Ensembl gene ENSG00000240927.
Homologues: Orthologues: chimpanzee Metazoa_SRP (99% identical), pig Metazoa_SRP (58% identical). Paralogues in human: RN7SL536P (82% identical), Metazoa_SRP (82% identical), RN7SL106P (82% identical), RN7SL238P (82% identical), RN7SL545P (82% identical), RN7SL759P (82% identical), RN7SL196P (80% identical), RN7SL286P (80% identical), RN7SL539P (80% identical), RN7SL796P (80% identical), RN7SL214P (79% identical), RN7SL736P (75% identical), and 704 more.